RN7SKP148 (RN7SK pseudogene 148)
Gene: Miscellaneous RNA gene on chromosome 5 (175,628,188 to 175,628,462, forward strand). Ensembl gene ENSG00000222111.
Homologues: Orthologues: chimpanzee 7SK (97% identical), guinea pig 7SK (67% identical), mouse Gm54577 (59% identical). Paralogues in human: RN7SKP37 (77% identical), RN7SKP45 (77% identical), RN7SKP9 (77% identical), 7SK (77% identical), RN7SKP133 (76% identical), RN7SKP217 (75% identical), RN7SKP118 (75% identical), RN7SKP180 (75% identical), RN7SKP211 (75% identical), RN7SKP255 (75% identical), RN7SKP47 (75% identical), RN7SKP203 (75% identical), and 284 more.